MUTYH (mutY DNA glycosylase)
Diseases named in the same sentence as MUTYH in open-access papers (continued):
Sharing a sentence is not in itself a finding about the gene and the disease.
polyposis (continued). "However, only MUTYH variant (p.G143E; dbSNP id: rs730881833) present in AML-M1 patient was reported as likely pathogenic for MUTYH associated Polyposis and Hereditary Cancer Predisposition Syndrome in ClinVar." (PMID 35350997, 2022). "MUTYH‐associated polyposis is caused by a biallelic variant in the MUTYH gene." (PMID 35128723, 2022). "The variant in MUTYH is pathogenic and leads to MUTYH-Associated Polyposis in a recessive manner." (PMID 32695137, 2020). "MUTYH causes an autosomal recessive polyposis syndrome, MUTYH-associated polyposis." (PMID 32133419, 2020). "Moreover, the germline mutation of MUTYH and increased mutagenesis in genomic DNA have been identified as the cause for autosomal recessive familial adenomatous polyposis, known as MUTYH-associated polyposis." (PMID 33149810, 2020). "In both MUTYH- as well as NTHL1-associated polyposis, the base excision repair pathway is affected." (PMID 27060000, 2016). "The remaining eight patients presented an attenuated polyposis burden (< 100 polyps), among whom five carried biallelic mutations in the MUTYH gene, one carried a novel APC duplication of exons 1–3, one presented a novel APC missense variant, and one was mutation-negative." (PMID 23561487, 2013). "In 2002, Al-Tassan and co-workers described for the first time a recessive form of inherited polyposis associated with germline mutations of MUTYH, a gene encoding a base excision repair (BER) protein that counteracts the DNA damage induced by the oxidative stress." (PMID 22876359, 2012). "MUTYH associated polyposis is a frequent inherited CRC predisposition, which can be mostly in a recessive form of inheritance (bi-allelic or compound mutations) but also as a dominant component, and therefore DNA screening of the MUTYH gene should look for both heterozygous and homozygous mutations." (PMID 19822006, 2009). "In a subset of individuals, a MUTYH mutation causes a recessively inherited polyposis condition, MUTYH-associated polyposis (MAP), which is characterized by a slightly increased risk of developing CRC and polyps/adenomas in both the upper and lower gastrointestinal tract." (PMID 19822006, 2009). "Because the carrier mutation rate in the MUTYH gene, is about 1% of patients with low or mild polyposis and it has been found that heterozygous MUTYH mutation carriers can have an increased risk for developing CRC (especially in MAP patients aged >55 years), this can be a dilemma." (PMID 19822006, 2009). "In studies of Polyposis patients (N=995), it has been found that 5-22% of the patients with 3-100 adenomas and 7.5-17% of those with over 100 adenomas had biallelic mutations in the MUTYH gene." (PMID 19506731, 2008). "Biallelic loss of NTHL1 or MUTYH results in NTHL1-associated polyposis (NAP) and MUTYH-associated polyposis (MAP), respectively." (PMID 41595502, 2026). "The genetic causes can be classified into different types of polyposis, such as familial adenomatous polyp (FAP), MUTYH-associated polyposis, Peutz–Jeghers syndrome, juvenile polyposis syndrome, and juvenile hyperplastic polyposis syndrome." (PMID 40232502, 2025). "In a large cohort of 8676 individuals with polyposis, 24% of them had a pathogenic APC or MUTYH alteration." (PMID 40095498, 2025). "All these facts make the p.Q82* of the NTHL1 gene screening reasonable in polyposis patients (especially in an unusual disease course), with APC, MUTYH, STK11, BMPR1A, and SMAD4 mutations excluded." (PMID 37834005, 2023). "This includes LS, APC-associated polyposis, Peutz–Jeghers Syndrome (PJS), Juvenile Polyposis Syndrome (JPS) and MUTYH-associated polyposis." (PMID 37258796, 2023). "In most polyposis patients with hundreds to thousands of colorectal adenomas, pathogenic germline variants in the APC or MUTYH gene are detected." (PMID 35675019, 2023).
polyposis (continued). "Some studies reported the presence of biallelic germline variants in the MUTYH gene in LLS cases, and MUTYH-associated polyposis can overlap with the LS phenotype by somatic inactivation of MMR genes." (PMID 36077770, 2022). "Recently, biallelic germline variants of the DNA glycosylase genes MUTYH and NTHL1 were linked to polyposis susceptibility." (PMID 36387175, 2022). "Fourteen relatives, all unaffected by cancer or polyposis, were genotyped for these MSH6 and MUTYH variants, identifying one additional carrier of both variants, five MSH6‐only carriers and four MUTYH‐only carriers." (PMID 32615015, 2020). "To date, two autosomal recessive polyposis syndromes have been identified, MUTYH-associated polyposis and NTHL1-associated polyposis." (PMID 27060000, 2016). "The aim of this study was to conduct a comprehensive molecular analysis to determine the spectrum of point mutations and large genomic rearrangements (LGR) in the APC and MUTYH genes in a series of 23 Brazilian polyposis patients." (PMID 23561487, 2013). "DNA sequencing of the complete coding region of the APC and MUTYH genes was performed in 23 unrelated Brazilian polyposis patients." (PMID 23561487, 2013). "Based on our findings, we recommend including APC and MUTYH in LS syndrome gene panels, as many patients harbor pathogenic variants in these genes despite lacking the typical polyposis phenotype." (PMID 40823072, 2025). "NTHL1 heterozygotes do not appear to be at clinically significant increased risk for polyposis and/or CRC and BC, but a slightly increased risk cannot be excluded, as has been described for patients with heterozygous variants in the MUTYH gene." (PMID 37727376, 2023). "Although patients M3 and M4 had no personal history of polyposis, both patients had the MUTYH c.1187G>A (p.G396D) variant." (PMID 32443704, 2020). "The detection of a pathogenic variant on MUTYH gene in two patients, 2/IV‐2 and 2/IV‐7, in our study may suggest a risk for MYH‐associated polyposis, and colon cancer in the future." (PMID 31207142, 2019). "In FAP syndrome, attenuated forms (AFAP) are caused by low penetrance mutations (missense mutations) in the main APC gene or by biallelic loss of the MYH gene (MAP, MUTYH-associated polyposis with autosomal recessive inheritance), encoding a protein of the Base Excision Repair complex (BER)." (PMID 28250766, 2017). "In this sense, a recent study demonstrated that up to 8% of APC/MUTYH-negative polyposis patients presented a deep intronic APC variant that led to an aberrant transcript." (PMID 23561487, 2013). "Approximately 30% of APC mutation-negative polyposis cases can be attributed to MUTYH biallelic mutations; on the whole, these account for less than 1% of all CRC cases." (PMID 22876359, 2012). "The frequency of biallelic carriers of 2 most prevalent Caucasian mutations, p.Y179C and p.G396D, among APC negative patients with polyposis was 2-40%, and the frequency of carriers of monoallelic MUTYH mutations among CRC patients was 0.9-4.2%." (PMID 21901162, 2011). "There are reports that patients heterozygous for MUTYH may also develop a phenotype of polyposis and because of the high carrier rate, ~1%, there can be compound heterozygotes of uncertain clinical significance." (PMID 19822006, 2009). "Twenty-four percent of the APC-negative patients carried biallelic MUTYH germline mutations, and showed an attenuated polyposis phenotype generally without extracolonic manifestations." (PMID 19531215, 2009). "Besides age, inherited genetic syndromes, such as Lynch syndrome (hereditary non-polyposis colorectal cancer), familial adenomatous polyposis, and MutY DNA Glycosylase (MUTYH)-associated polyposis, are considered non-modifiable risk factors for CRC." (PMID 31906264, 2020). "However, in a case-control study of Indian Polyposis patients (cases: N=120 and controls: N=100), merely one case and one control were found to be heterozygote for E480X, while no other MUTYH mutations were found." (PMID 19506731, 2008).
polyposis (continued). "However, another paper on MUTYH-associated polyposis and immunostaining did not confirm such a finding showing strong MUTYH cytoplasmatic expression in the tumoral tissue of non-MUTYH carriers, suggesting that immunohistochemistry cannot be used to discriminate MUTYH-mutated from unmutated cases." (PMID 38790183, 2024). "Unlike APC and MUTYH polyposis, POLD1/POLE syndrome is characterized by the development of extraintestinal tumors, including endometrial, ovarian, brain, and pancreatic cancers." (PMID 39661238, 2025). "Among all the non-MMR genes, APC, MUTYH and SMAD4 are well known to be implicated in CRC, specifically in polyposis." (PMID 30256826, 2018). "No alterations in APC or MUTYH genes were present in the polyposis group, and alterations in MUTYH or the MMR genes/proteins and tumor microsatellite instability were absent in the early-onset CRC group." (PMID 28423643, 2017). "Both patients had a clear polyposis phenotype and early age of onset, without detectable pathogenic germ line variants in the APC gene or MUTYH gene." (PMID 25604157, 2015). "Finally, our patient series includes 17 families with no germline APC or MUTYH mutation detected, although ten of them belong to the classical FAP group with profuse polyposis." (PMID 26446593, 2016). "Our ultimate goal is to enable an appropriate approach to prophylactic strategies in Polish families with polyposis, especially in those patients whose APC, MUTYH, STK11, BMPR1A, and SMAD4 gene testing showed no abnormalities." (PMID 37834005, 2023). "Patients with multiple polyps presented 10–100 polyps, being the main precursor lesion adenomatous, serrated or a combination of adenomatous and serrated polyps with an age of onset < 70 and no alterations in the APC or MUTYH genes." (PMID 28423643, 2017).
mutyh-associated polyposis (68 papers, 2008 to 2025). An autosomal recessive hereditary neoplastic syndrome caused by mutations in the MUTYH gene on chromosome 1p34.1. "Germline mutations of MUTYH are associated with multiple colorectal polyposis or adenomas, termed MUTYH-associated polyposis (MAP)." (PMID 40469416, 2025). "An autosomal recessive polyposis condition called MUTYH-associated polyposis (MAP) is brought on by germline mutations in the MUTYH gene." (PMID 37313091, 2023). "MUTYH mutations inherited in the germline in humans cause an autosomal recessive syndrome (MUTYH-associated polyposis, MAP) characterised by intestinal adenomatous polyposis and an elevated risk of early onset colorectal and duodenal cancer." (PMID 35803914, 2022). "Such genes include MUTYH with the autosomal recessive inherited disease MAP (MUTYH-associated polyposis)." (PMID 36553592, 2022). "This MUTYH variant is a known common pathogenic missense variant known to cause MUTYH-associated polyposis (MAP) in Western populations when detected in homozygous or compound heterozygous state." (PMID 33917078, 2021). "MUTYH is a DNA repair gene whose biallelic germline variants cause MUTYH-associated polyposis (MAP) syndrome." (PMID 30564557, 2018). "Biallelic germline MUTYH mutations are responsible for MUTYH-associated polyposis (MAP), a recessively heritable colorectal polyposis that is linked to an increased risk of CRC." (PMID 26109431, 2015). "The importance of protection against ROS-induced DNA damage is illustrated by the association between MUTYH gene mutations and MUTYH-Associated Polyposis (MAP), a heritable syndrome linked to an increased colorectal cancer risk." (PMID 25638157, 2015). "Patients with two mutations in the MUTYH gene develop the MUTYH-associated polyposis (MAP) syndrome." (PMID 24039736, 2013). "MUTYH mutations are the cause of MUTYH-associated Polyposis (MAP) and monoallelic MUTYH missense mutations have been suggested to confer an increased CRC risk when combined with MSH6 mutations." (PMID 24040339, 2013). "Biallelic mutations in MUTYH predispose to a familial adenomatous polyposis variant called MUTYH-associated polyposis (MAP)." (PMID 23203191, 2012). "Biallelic inactivating germline mutations in the base excision repair MUTYH (MYH) gene have been shown to predispose to MUTYH-associated polyposis (MAP), which is characterized by multiple colorectal adenomas and carcinomas." (PMID 20848659, 2010). "However, the mechanistic progression from germline MUTYH mutations to MUTYH-Associated Polyposis (MAP) is incompletely understood." (PMID 35803914, 2022). "It is not known whether adenomatous polyposis caused by bi-allelic germline mutations in the MUTYH gene (MUTYH-associated polyposis (MAP)) is also associated with BE." (PMID 32088803, 2020). "Thus far, two autosomal recessive Mendelian CRC syndromes have been described, namely MUTYH-associated polyposis (MAP) caused by biallelic mutations in the MUTYH gene and NTHL1-associated polyposis caused by biallelic mutations in the NTHL1 gene." (PMID 28445943, 2017). "MutYH-associated polyposis (MAP) is caused by biallelic mutations of the MUTYH gene (MIM *604933)." (PMID 25860647, 2015). "In this group, fifteen patients were suspected to have MUTYH-Associated Polyposis (MAP) and thus screened for pathogenic variants (PVs) in the MUTYH gene." (PMID 40554495, 2025). "MUTYH-associated polyposis (MAP) is a recessive adenomatous polyposis syndrome caused by constitutional PVs in MUTYH; a gene that encodes MYH glycosylase, which is part of the DNA base excision repair (BER) system." (PMID 40237887, 2025). "Another hereditary syndrome is the polyposis associated with a mutation in the MUTYH gene (MUTYH-Associated Polyposis, MAP), which typically occurs in young adults (40–60 years)." (PMID 39201522, 2024). "Biallelic germline mutation of the BER glycosylase MUTYH causes higher risk of MUTYH-associated polyposis (MAP), predisposing carriers to colorectal cancers." (PMID 36362142, 2022).
mutyh-associated polyposis (continued). "More importantly, 16–40% of patients with less than 100 polyps present the biallelic inactivation of the MUTYH-based excision repair gene, a condition called MUTYH-associated polyposis (MAP)." (PMID 33374459, 2020). "Biallelic (homozygous or compound heterozygous) MUTYH variants occur in 0.01–0.04% of European descent populations and cause MUTYH-associated polyposis syndrome (MAP), which predisposes patients to develop colorectal polyps and colorectal cancer." (PMID 30564557, 2018). "Investigation revealed that this gene is involved in DNA base excision repair, and biallelic mutations of the MUTYH gene is related to the development of multiple adenomas, a syndrome known as MUTYH-associated polyposis or MAP." (PMID 29147111, 2017). "MUTYH is the responsible gene for MUTYH-associated polyposis (MAP), a hereditary disease characterized by colorectal polyposis and carcinoma(s)." (PMID 29098062, 2017). "In later studies autosomal recessively inherited mutations in the DNA repair gene MUTYH were found to give rise to a specific subtype of polyposis, referred to as MUTYH-associated polyposis (MAP)." (PMID 27279102, 2016). "Clinically, biallelic germline inactivating MUTYH mutations are known to predispose an individual to MUTYH-associated polyposis (MAP: MIM #608456), a hereditary disorder characterized by multiple colorectal polyps and carcinoma(s)." (PMID 24799981, 2014). "Biallelic inactivating germline mutations in the MUTYH gene predispose to MUTYH-associated polyposis (MAP; MIM# 608456), an autosomal recessive disorder characterized by multiple colorectal adenomas and carcinomas." (PMID 20848659, 2010). "MUTYH-associated polyposis (MAP) is a disorder caused by bi-allelic germline MUTYH mutation, characterized by multiple colorectal adenomas." (PMID 20687945, 2010). "Recently, a new type of colorectal adenomatous polyposis has been described, MUTYH-associated polyposis (MAP) or MUTYH-associated CRC (MIM#608456)." (PMID 18433509, 2008). "These variants were most frequent in HFE (n = 207, 5.21%), MUTYH (n = 91, 2.29%) and ATP7B (n = 73, 1.84%), associated with hereditary haemochromatosis, MUTYH-associated polyposis (MAP), and Wilson disease." (PMID 40332002, 2025). "MUTYH-associated polyposis (MAP) is caused by GPVs of the MUTYH gene and is recessively inherited." (PMID 37258796, 2023). "MUTYH-associated polyposis (MAP) was first described when two inherited germline mutations in the MUTYH gene (Y165C and G382D) were identified in three siblings with clinical symptoms of familial adenomatous polyposis (FAP), an inherited condition that predisposes to colorectal cancer (CRC)." (PMID 36176767, 2022). "A subset of patients with multiple colorectal adenomas and no APC germline variants have been found to carry biallelic variants in the base excision repair gene MUTYH (MIM# 604,933), causing MUTYH-associated polyposis (MAP; MIM# 608,456)." (PMID 33683519, 2022). "Biallelic pathogenic variants in the MUTYH gene cause MUTYH-associated polyposis (MAP)." (PMID 35320498, 2022). "The direct evidence regarding the link between BER and MMR was shown in MUTYH-associated polyposis (MAP), where MUTYH interacts with MMR gene products." (PMID 32872214, 2020). "MUTYH germline mutations of BER (pathways 5,7,19) cause MUTYH-associated polyposis (MAP), a disorder similar to familial adenomatous polyposis (FAP), caused by mutations in the APC gene." (PMID 33121134, 2020). "Germline mutations in MUTYH cause MUTYH-associated polyposis (MAP)." (PMID 31253177, 2019). "MUTYH-associated polyposis (MAP), an autosomal recessive condition caused by biallelic pathogenic variants in MUTYH, is characterized by multiple colorectal adenomas arising in adulthood and increased colorectal cancer risk." (PMID 27014339, 2016). "MUTYH-associated polyposis (MAP), an autosomal recessive disorder, is associated with biallelic germline mutations in MUTYH and was first reported in 2002." (PMID 26273655, 2015).
mutyh-associated polyposis (continued). "We undertook the MLPA analysis because MUTYH-associated polyposis (MAP) is an autosomal recessive disease and the proband’s parents may have been carriers of the MUTYH mutation." (PMID 27081559, 2015). "The importance of this MUTYH-initiated pathway is illustrated by the fact that biallelic mutations in the MUTYH gene are associated with a hereditary colorectal cancer syndrome termed MUTYH-associated polyposis (MAP)." (PMID 23450852, 2013). "Importantly, 16%–40% of patients with less than 100 polyps carry the bi-allelic inactivation of the MUTYH based-excision repair gene, a condition called MUTYH-associated polyposis (MAP)." (PMID 23965959, 2013). "MUTYH is involved in the BER pathway, which is best known for MUTYH-associated polyposis (MAP)." (PMID 34026622, 2021). "Phenotypically similar to the AFAP is MUTYH-associated polyposis (MAP; MIM# 608456), resulting from biallelic pathogenic variants in the MUTYH gene." (PMID 41204315, 2025). "Patients with germline MUTYH mutations have an elevated adenoma formation rate, and consequently are at increased risk of CRC in a clinical syndrome known as MUTYH-associated polyposis (MAP)." (PMID 37573406, 2023). "Since biallelic mutations in MUTYH cause MUTYH-Associated Polyposis (MAP) and the sample does not have another co-occuring MUTYH mutation, this suggests that PT219 is a carrier of MUTYH mutation." (PMID 28526081, 2017).